ENSG00000269741 (novel transcript)
Gene: Protein-coding gene on chromosome 19 (50,996,018 to 51,009,581, reverse strand). Ensembl gene ENSG00000269741.
Genetic constraint (gnomAD): Missense variants: 346 observed, 336.21 expected, observed/expected ratio (o/e) 1.03, 90% interval 0.94 to 1.12. Synonymous variants: 122 observed, 129.7 expected, observed/expected ratio (o/e) 0.94, 90% interval 0.81 to 1.09.